A2M (alpha-2-macroglobulin)
Diseases named in the same sentence as A2M in open-access papers (continued):
Sharing a sentence is not in itself a finding about the gene and the disease.
tumor (continued). "Second, we test if α2M can bind to tumor antigens released into the tumor microenvironment (and beyond) and whether these pre-formed α2M-tumor antigen complexes are immunogenic." (PMID 23226267, 2012). "Thus complexing of singular, defined tumor-derived peptide antigens to α2M in vitro has been the principle way of eliciting immune responses that target murine tumors." (PMID 23226267, 2012). "To determine if the nature or site of the tumor affected the formation of the immunogenic complexes, we established MethA tumors as a solid intradermal tumor or as peritoneal ascites and tested the immunogenicity of α2M isolated from serum of mice bearing each type of tumor." (PMID 23226267, 2012). "α2M-tumor antigen complexes may thus play a role in immuno-editing of the tumor phenotype." (PMID 23226267, 2012). "The answer may be in three parts; first, α2M-tumor antigen complexes may indeed immunize the host, however tumor growth may progress because it becomes immuno-insensitive through a variety of mechanisms including loss of antigen and/or MHC or gain of suppressor functions." (PMID 23226267, 2012). "There is also evidence that A2M regulates tumor cell growth by upregulating PTEN and inhibiting tumour-promoting signalling pathways such as PI3K/AKT and SMAD, making A2M a promising anticancer drug which should also be further assessed." (PMID 38612805, 2024). "According to the authors, the malignant properties of the tumour can be inhibited by acting on the low-density lipoprotein receptor-related protein 1 (LRP1), which is a receptor for A2M." (PMID 38612805, 2024). "There is evidence that A2M regulates tumor cell growth by upregulating PTEN and inhibiting tumour promoting signalling pathways such as PI3K/AKT, SMAD, and A2M is likely to become a new type of therapeutic drug." (PMID 34979994, 2022). "On the other hand, gene expression analyses confirmed that proteins related to the complement activation, such as C1QA, SERPING1, A2M, ITGAM and ITGB2, were significantly overexpressed in P3 tumours, compared to P1 and P2 subtypes." (PMID 31560832, 2019). "Last and most important targeting α2M*/CS-GRP78 with C38 Mab abrogates α2M* and acetate-induced histone and other protein acetylation necessary for tumor proliferation and survival under hypoxic stress." (PMID 29296215, 2017). "In NSCLC, A2M expression was decreased in tumor cells compared to non-malignant lung tissue, while its receptor LRP1 was upregulated in the tumor stroma, indicating a potential compensatory mechanism." (PMID 40649877, 2025). "Additionally, the upregulation of A2M and SERPINF1 suggested enhanced immune-modulatory and anti-angiogenic effects, potentially limiting tumour invasion and vascularisation." (PMID 40725093, 2025). "It is particularly noteworthy that 6 chemokine receptors in GO term “chemokine binding”, including CXCR4, CCR5, CCR1, CCRL2, CMKLR1 and A2M, are specific expressed in FGFR2+ fibrocytes before arriving in tumor sites suggesting their possible roles in fibrocyte recruitment." (PMID 35941662, 2022). "The A2M protein levels were lower based on stages and tumor histologic grades, but were not stage or grade dependent." (PMID 35625488, 2022). "In line with our results, it has been shown that decreased protein levels in cancerous samples of A2M, C4BP and IGHM/MUCB disturb the otherwise protective role of these proteins and may abet tumor development." (PMID 32408476, 2020). "A2M* is a ligand of LRP1, which has been shown to regulate cytoskeleton organization, interaction with the extracellular matrix and affects migration and invasion of various non-tumour and tumour cells." (PMID 29281661, 2017). "α2M and gp96 complexed to CMS5-derived peptides were able to elicit immune responses capable of significantly retarding the growth of CMS5 tumor cells." (PMID 23226267, 2012).
tumor (continued). "In addition, A2M presents anti-tumorigenic activity that acts as an inhibitor of central signaling pathways (e.g., phosphatidylinositol 3-kinase (PI3K), protein kinase B (AKT), and SMAD) and modulates tumor cell adhesion, migration, and growth." (PMID 37174723, 2023). "Thus the relevance of these two forms of α2M in vivo has been questioned and in our study here we do not observe any conformational changes in α2M isolated from tumor bearing mice compared to α2M from non-tumor bearing mice." (PMID 23226267, 2012). "We do not rule out the possibility that the tumor antigen bound by α2M may be a protein as α2M is known to chaperone a large family of proteins." (PMID 23226267, 2012). "α2M from mice bearing irrelevant tumors also failed to affect tumor growth (data not shown)." (PMID 23226267, 2012).
infection (24 papers, 2010 to 2025). The state of being infected such as from the introduction of a foreign agent such as serum, vaccine, antigenic substance or organism. "Furthermore, this virus, which proved to be lethal after infection in pigs, also suppressed A2M, whose dysregulation has been linked with tissue inflammation and several cytokine-related diseases." (PMID 40006915, 2025). "In addition to α-2M and lipocalin-1, we identified several additional proteins that may protect the uterus against infection and tissue damage associated with implantation." (PMID 28405395, 2017). "In the clinical phase of infection, proteins such as prothrombin (fragment), complement component 4 binding protein alpha, and alpha-2-macroglobulin are upregulated, indicating an immune response." (PMID 40646861, 2025). "Previous research has already shown that DENV virions can also bind LRP1 ligands, and in the case of α2M, it was proven that this interaction leads to increments in infection." (PMID 39599807, 2024). "A2M is known as a human protease inhibitor, which is potentially involved in host defense and infection." (PMID 39639867, 2024). "A2M is a protease inhibitor known to inhibit the proteases produced by parasites during host infection process." (PMID 31783772, 2019). "We found three α2M isoforms in groupers, all of which were significantly upregulated in grouper gill and spleen post-infection (data unpublished)." (PMID 27923398, 2016). "In P. monodon, alpha-2-macroglobulin has been also shown to have the ability to bind to Pm-syntenin whose transcript was up-regulated upon WSSV infection." (PMID 20626881, 2010). "A higher abundance of alpha-2-macroglobulin, fibrinogen and IgG proteins in the Streptococcus group may act negatively on the host response to the infection by S. dysgalactiae." (PMID 37889706, 2023). "Since mammalian alpha-2-macroglobulin is a multifunctional protein with important roles in inflammation, immunity, and infection, secreted S. mansoni alpha-2-macroglobulin may affect the host and play a role in the infection process." (PMID 37817269, 2023). "Both alpha-2-macroglobulin isoforms detected in the gill at various timepoint post-re-infection may be indicative of a host immune response to local colonization." (PMID 34062978, 2021). "Taken together, these observations suggest that lipocalin-1 may work alongside α2M to protect the uterine environment against infections, and its lipid-binding may involve sequestration of toxic lipid peroxidation products created under condition of oxidative stress." (PMID 28405395, 2017). "Expression levels of alpha-2-macroglobulin-like (A2M), decay accelerating factor (DAF), and minus strand C1 inhibitor (SERPING1) were unaffected by infection." (PMID 25496447, 2014). "Interestingly, DEGs associated with neurodegenerative diseases, such as NLRP3, CSF1, and A2M, exhibit higher expression in the ITA infection group." (PMID 40723822, 2025). "According to Li & Lu32, α2M was able to inhibit the extracellular protease of A. hydrophila (AhECPase) in carp, for these authors this APP may play a role in the resistance to infection by this pathogen." (PMID 30886242, 2019). "The expression of 38 proteins in the acute-phase response signalling pathway changed over the course of the infection, with maximum upregulation observed from as early as 42 h, e.g. for HRG and alpha-2-macroglobulin, to as late as 312 h for complement C1 subcomponent and retinol-binding protein." (PMID 27412694, 2016). "Also, we showed that α2M*, a ligand of LRP1, directly binds DENV virions and favors DENV infection." (PMID 39599807, 2024). "Although the interaction between A2M and mycobacterial proteases has not yet been identified, the elevated serum A2M level in MAP-infected animals might be in response to the release of MAP serine protease during infection." (PMID 33748212, 2021).
neurodegenerative disease (4 papers, 2009 to 2025). A disorder of the central nervous system characterized by gradual and progressive loss of neural tissue and neurologic function. "The interest in the influence of α2M in AD is not new, as earlier reports suggested an association between α2M polymorphisms and an increased risk of neurodegenerative diseases." (PMID 34945282, 2021).
cardiovascular disease (3 papers, 2021 to 2023). "Previous studies have demonstrated that inflammatory proteins contribute to cardiovascular diseases, including Alpha-2-Macroglobulin (A2M), Fetuin A, Alpha-1-Acid Glycoprotein (AGP), Serum Amyloid P component (SAP), and Adipsin." (PMID 36582735, 2022).
adenocarcinoma (2 papers, 2012 to 2024). A common cancer characterized by the presence of malignant glandular cells. "Similar to our studies, low A2M expression was shown in adenocarcinoma tissues compared to healthy ones." (PMID 38612805, 2024). "Indeed, we found that cathepin B (CTSB), serpin peptidase inhibitor, clade B, member 11 (SERPINB11) and alpha 2 macroglobulin (A2M) genes are most abundant in GE of chicken adenocarcinoma." (PMID 22496782, 2012).
brain disease (2 papers, 2022 to 2023). "A significant elevation in alpha-2-macroglobulin, a known metal-binding biomarker correlated with brain disease burden, was observed on the gene and protein levels in the olfactory mucosa cells of AD patients." (PMID 35456941, 2022). "Based on the multifunction of these proteins in several brain diseases, we first propose that Gc-globulin, ApoA1, PI3K/AKT pathway, and acute phase response proteins (hemopexin and cluster of alpha-2-macroglobulin) could be potential candidates for the diagnosis and treatment of SAE." (PMID 36600206, 2023).
kidney disease (2 papers, 2013 to 2024). "ADAM19 (Meltrin-beta) is the upstream regulator for alpha-2-macrogulbulin (A2M) whose role in renal disease has been identified in several studies." (PMID 24339887, 2013). "Whether NFAT5 regulation of A2M is important to non-diabetic kidney disease requires further study." (PMID 39595620, 2024).
liver (1 paper, 2016). "Adiponectin is important in astrocyte-neuron amyloid beta metabolism, with the effects of adiponectin on brain–liver amyloid clearance determined by proteins such as alpha 2 macroglobulin and TSP-1." (PMID 28248224, 2016).
myopathy (1 paper, 2015). A disease of the muscle in which the muscle fibers do not function properly. "Birds suffering from this myopathy exhibit down-regulation of eight hemostatic genes (A2M, FGA, FGB, FGG, KNG1, SERPINC1 and VWF) and up-regulation of four other coagulation genes (F5, F10, PROS1 and F2R)." (PMID 26445145, 2015).
proliferative retinopathies (1 paper, 2019). "In this sense, our results show that the migratory capacity of MIO-M1 cells induced by α2M* depends on the intracellular distribution and traffic of LRP1 to the PM, which may have special clinical connotations in the treatment of proliferative retinopathies." (PMID 31519919, 2019).
A2M also shares sentences with these, for which no sentence is quoted: endometritis (3 papers); astrocytoma (2); colon cancer (2); glioma (2); infectious disease (2); non-small cell lung carcinoma (2); pancreatic cancer (2); radiation pneumonitis (2); retinal degeneration (2); abdominal aortic aneurysm (1); acute pancreatitis (1); alcoholic liver diseases (1); anterior segment dysgenesis (1); antithrombin deficiency (1); Azoospermia (1); bacterial infections (1); bacterial meningitis (1); benign breast disease (1); bipolar disorder (1); carpal tunnel syndrome (1); celiac disease (1); cervical cancer (1); cholestasis (1); chronic GVHD (1); chronic hepatitis B (1); chronic hepatitis C (1); chronic lung disease (1); chronic periodontitis (1); clear cell carcinomas (1); Cognitive impairment (1).
A further 49 diseases each share a sentence with A2M in 1 paper.